MC4R (melanocortin 4 receptor)
Diseases named in the same sentence as MC4R in open-access papers (continued):
Sharing a sentence is not in itself a finding about the gene and the disease.
Obesity (continued). "Underlying these rare forms of obesity are key signaling pathways, such as the leptin–melanocortin-4 receptor (MC4R) pathway, which centrally regulates energy balance and food intake through select hypothalamic structures." (PMID 39856371, 2025). "Specifically, FTO polymorphisms have been linked to increased obesity risk and altered eating behaviors, while MC4R variants can influence appetite and satiety." (PMID 41228239, 2025). "A recent study demonstrated that polygenic scores, derived from well-established obesity-associated loci such as FTO (Fat Mass and Obesity Associated) and MC4R, interact with lifestyle behaviors." (PMID 41009961, 2025). "MC4R remains the most commonly implicated gene in monogenic obesity, with heterozygous loss-of-function variants reported in 2–5% of individuals with early-onset severe obesity." (PMID 40428329, 2025). "In contrast, monogenic obesity, caused by a single, rare mutation in genes like LEP, LEPR, POMC, or MC4R, accounts for less than 1% of obesity cases." (PMID 40564803, 2025). "Loss-of-function mutations or variants that impair MC4R signaling can disrupt the normal satiety signaling pathways, leading to hyperphagia and obesity." (PMID 41002740, 2025). "Variants in BSN were associated with markedly increased obesity risk, even surpassing that of well-known monogenic obesity genes such as MC4R." (PMID 41009961, 2025). "We conclude that tirzepatide is an effective treatment for the most common genetic subtype of obesity, MC4R deficiency." (PMID 40858971, 2025). "Natural history studies, patient and caregiver surveys, and clinical trials of patients with rare MC4R pathway diseases associated with hyperphagia and obesity have characterized both the presentation and burden of hyperphagia." (PMID 40560452, 2025). "MC4R mutations are the most common cause of monogenic obesity in humans, but, in contrast to mice, human MC4R mutations lead to an early onset of obesity." (PMID 40702736, 2025). "The GPCR melanocortin 4 receptor (MC4R) localizes to cilia in hypothalamic neurons, and MC4R mutations are typically associated with obesity, a symptom commonly observed in many ciliopathies, including Bardet-Biedl syndrome and Alström syndrome." (PMID 40301543, 2025). "Recent studies have identified new genetic regulatory mechanisms and potential biomarker regions for the POMC gene and MC4R secondary messenger pathway associated with obesity." (PMID 40001512, 2025). "A recent study showed that monoallelic, loss-of-function mutation of GNAS led to obesity by impeding MC4R signaling via defective interaction between Gαs and MC4R." (PMID 39237720, 2025). "Melanocortin 4 receptor (MC4R) is another obesity-associated gene that is located on chromosome 18q22 and consists of a single exon." (PMID 40353441, 2025). "We note that the MC4R[V103I] variant, which protects against obesity, displays increased binding to β-arrestin." (PMID 39899600, 2025). "Targeted treatment options for monogenic obesity include pharmacologic interventions such as setmelanotide, an MC4R agonist, and metreleptin for congenital leptin deficiency." (PMID 40636093, 2025). "Here we replicate earlier studies showing that blood pressure is reduced in people with obesity due to MC4R deficiency, an effect that is likely to be driven by impaired SNS tone." (PMID 41102563, 2025). "In contrast, certain rare gain-of-function mutations in MC4R have been associated with reduced appetite and protection against obesity." (PMID 41002740, 2025). "Although our study did not include genetic testing, certain forms of obesity do have a strong genetic basis—such as monogenic obesity or melanocortin 4 receptor (MC4R) deficiency—that predisposes individuals to binge eating or other forms of disordered eating." (PMID 40169756, 2025). "A study on the loss-of-function MC3R Ala33Thr variant pointed towards obesity-related pathways controlled by G-proteins other than Gαs, similar to MC4R." (PMID 40001512, 2025).
Obesity (continued). "The role of the melanocortin system in energy balance control is also shown by monogenic disorders, with mutations in the Mc4r gene being the most common monogenic type of obesity." (PMID 40474775, 2025). "Our studies have demonstrated that MRAP2 variants associated with human obesity impair multiple aspects of MC4R signaling." (PMID 39807633, 2025). "In particular, BBS is a syndromic MC4R pathway disease with hallmark symptoms of hyperphagia and early-onset severe obesity." (PMID 40847358, 2025). "The mutations in MC1R, MC2R, MC3R, and MC4R genes are associated with risk of melanoma, familial glucocorticoid deficiency, obesity, and type 2 diabetes mellitus, respectively." (PMID 41002740, 2025). "Loss-of-function mutations of MC4R result in increased food intake and decreased energy expenditure, as well as severe early-onset obesity in many human populations." (PMID 40001512, 2025). "Findings indicate that individuals with obesity due to MC4R deficiency have lower cholesterol and triglyceride levels, as well as reduced cardiovascular risk." (PMID 41102563, 2025). "According to the results of the genome-wide association studies in humans, the most remarkable genes, associated with an increased risk of obesity, are MC4R, BDNF, LEP, LEPR and FTO." (PMID 40035963, 2025). "In humans, heterozygous loss-of-function mutations in MC4R are the most common monogenic cause of obesity." (PMID 40636449, 2025). "SIM1 acts downstream of MC4R, and both can cause monogenic obesity via autosomal dominant inheritance." (PMID 40428410, 2025). "While FTO is exclusively polygenic, MC4R represents a unique case: rare mutations cause monogenic obesity, whereas common polymorphisms act as major polygenic risk factors." (PMID 41302083, 2025). "In contrast, patient #6 (LEPR) and patients #11 and #14 (MC4R) carried pathogenic variants in genes typically associated with isolated obesity, but exhibited additional syndromic features." (PMID 40523925, 2025). "First discovered in Europeans, single-nucleotide polymorphisms (SNPs) in FTO and close to MC4R are obesity-susceptibility loci that extensively replicate across various ancestries." (PMID 41302083, 2025). "Mutations in the melanocortin-4 receptor (MC4R) gene are the most common, accounting for approximately 4–6% of monogenic obesity cases." (PMID 40149731, 2025). "The combined effects of common variants or epistasis in FTO and MC4R have been investigated, showing significant effects on obesity and related traits in children and adolescents." (PMID 41082226, 2025). "Loss-of-function mutations in the MC4R gene (e.g., frameshift variant c.732_735delCAGT) disrupt hypothalamic melanocortin-4 receptor signaling, leading to dominantly inherited early-onset obesity." (PMID 40452923, 2025). "In the GOOS cohort, a clinically ascertained group of people with severe early onset obesity, we found the prevalence of LoF MC4R variants to be 4.1%." (PMID 41102563, 2025). "Loss-of-function mutations in the Mc4r, Pomc, or Mrap2 genes lead to marked hyperphagia, early-onset obesity, and enhanced somatic growth in rodent models." (PMID 40956393, 2025). "The notion that MC4R is downstream of leptin targets is supported by the effectiveness of MC4R agonism to reduce hyperphagia and obesity in leptin-deficient individuals." (PMID 41251447, 2025). "This study aims to examine the clinical, metabolic, and genetic characteristics of a patient with severe early-onset obesity and his family, to assess the contribution of an MC4R variant to the observed phenotype." (PMID 40428329, 2025). "When the phenotypes of patients with MC3R and MC4R mutations were compared, both genes were found to be involved in severe early-onset obesity." (PMID 40001512, 2025). "In this cohort, variants in the MC4R gene were the most common cause of obesity, with the variant c.485C>T, p.T162I being the most frequently observed mutation in five patients." (PMID 40149731, 2025).
Obesity (continued). "Heterozygous mutations in the MC4R represent the predominant genetic aetiology of monogenic obesity." (PMID 41226372, 2025). "Here to investigate the possible role of MC4R in human lipid metabolism, we studied a clinically ascertained cohort of people with severe obesity in whom variants in MC4R were identified." (PMID 41102563, 2025). "The second gene containing variants with replicated associations with obesity and related phenotypes is MC4R, which encodes for a receptor specific to the heptapeptide core common to adrenocorticotropic hormone and α‐, β‐, and γ‐MSH." (PMID 41082226, 2025). "Obesity has been associated with MC4R loss-of-function mutations through the malfunction of the Gαs-activated cAMP secondary messenger pathway." (PMID 40001512, 2025). "Genetic polymorphisms or variations in the MC4R gene can influence receptor function and have significant implications for body weight regulation, satiety, and the risk of obesity." (PMID 41002740, 2025). "Variants in genes like FTO and melanortin-4 receptor (MC4R) have been consistently linked to BMI and fat distribution, highlighting the genetic underpinnings of obesity." (PMID 40149950, 2025). "Loss-of-function mutations in the genes encoding POMC, MC3R, and MC4R can lead to the dysregulation of energy expenditure and feeding balance, early-onset obesity, and developmental dysregulation." (PMID 40001512, 2025). "SNPs including fat mass and obesity-associated (FTO), brain-derived neurotrophic factor (BDNF), and melanocortin 4 receptor (MC4R) have also been implicated in obesity in the Japanese population." (PMID 40074353, 2025). "Deletion of the MRAP2 gene from mice on various genetic backgrounds is associated with extreme obesity, increased fat mass and visceral adiposity, analogous to MC4R knockout mice." (PMID 41401256, 2025). "Within MC4R, two well-characterized polymorphisms, Ile251Leu and Val103Ile, have protective associations, demonstrating reduced obesity risk among carriers." (PMID 41302083, 2025). "MC4R has been described to predominantly signal by the Gs-cAMP pathway, and ~ 75% mutations in MC4R that are associated with severe early onset obesity impair cAMP signaling." (PMID 39807633, 2025). "Any disruption in ligands or receptors involved in melanocortin signaling, such as rare, pathogenic mutations in LEP, LEPR, or MC4R encoding melanocortin 4 receptor, lead to early-onset severe obesity." (PMID 39237720, 2025). "Among 7,719 people from the Genetics of Obesity Study cohort, we identified 316 probands and 144 adult family members with loss-of-function (LoF) MC4R mutations." (PMID 41102563, 2025). "Recent studies have highlighted that polymorphisms in genes such as FTO and the Melanocortin-4 Receptor gene (MC4R) influence susceptibility to post-treatment obesity, enabling risk stratification and personalized intervention planning." (PMID 41228239, 2025). "A melanocortin 4 receptor (MC4R) agonist, setmelanotide (Set), is used to treat obesity caused by abnormal melanocortin and leptin signaling." (PMID 40232848, 2025). "Mice and humans with loss of function mutations of MC4R show enhanced weight gain and variants in MC4R are associated with resistance to obesity." (PMID 40356280, 2025). "MC4R deficiency also causes obesity associated with increased food intake and reduced energy expenditure in mice." (PMID 38175730, 2024). "Melanocortin-4 receptor (MC4R) mutations are the most frequent monogenic causes of severe early onset human obesity." (PMID 38674326, 2024). "Association between SNPs in FTO and MC4R gene with obesity were widely replicated in different ethnic groups." (PMID 38279121, 2024). "Mice deficient in melanocortin 4 receptor (MC4R), which is expressed in the hypothalamic nuclei and regulates appetite, also develop hyperphagic obesity, insulin resistance, hyperlipidemia, and hepatic steatosis." (PMID 38672461, 2024).
Obesity (continued). "Patients with SRC1 mutations and severe obesity have been enrolled in phase 2 clinical trials of setmelanotide, an MC4R agonist, approved for obese patients with POMC or LEPR mutations." (PMID 38397265, 2024). "For example, one study in Kuwait identified a genetic variant (rs17782313) close to the melanocortin 4 receptor (MC4R) gene as associated with obesity in its Kuwaiti cohort." (PMID 39544590, 2024). "The MC4R gene is undisputedly the most important gene involved in monogenic obesity, and MC4R variants are commonly found in studies exploring polymorphisms in non-monogenic forms of obesity." (PMID 39876968, 2024). "Here, large-scale genome-wide association studies (GWAS) identified obesity-related SNPs for three novel genes of Melanocortin-4 Receptor (MC4R), Caveolin (CAV), and Cryptochrome (CRY)." (PMID 38685080, 2024). "The knowledge of motivational differences caused by MC4R deficits reveals a potential new clinical target for the treatment of obesity in the underlying mechanisms of the dopamine reward circuitry connected to MC4R receptors." (PMID 39741559, 2024). "The polymorphism rs17782313 located downstream of MC4R, has been associated with overweight and obesity in many studies." (PMID 39203789, 2024). "In this study, we designed the pair-matched case-control study based on the cross-sectional data and found that MC4R gene polymorphisms were determinants of obesity in Tibetan." (PMID 38279121, 2024). "MC4R mutations are the most common cause of monogenic obesity and are associated with hyperphagia, increased body length, reduced energy expenditure, abnormal glucose and lipid metabolism, and decreased heart rate and blood pressure." (PMID 38175730, 2024). "Patients with mutations in the leptin-melanocortin pathway and BBS often receive dietary and exercise counseling similar to those with polygenic obesity, yet they show limited response to these lifestyle changes, as seen in MC4R deficiency." (PMID 39777073, 2024). "Mutations inducing loss of function of several genes within this pathway, including mutations in POMC, LepRb, or MC4R genes, have been shown in other in vivo studies to cause early-onset severe obesity." (PMID 38540381, 2024). "Deletion of the MRAP2 gene from mice on a variety of genetic backgrounds is associated with extreme obesity, increased fat mass and visceral adiposity, analogous to MC4R knockout mice." (PMID 39574659, 2024). "The most common monogenic form of obesity is associated with mutations in the MC4R gene, followed by mutations in the LEPR, POMC, PCSK1, and LEP genes." (PMID 39777073, 2024). "In this study, we functionally characterized 17, predominantly heterozygous, MC4R variants identified in our patients with early-onset severe obesity." (PMID 38567654, 2024). "Mutations in some GPCRs, such as the melanocortin receptor type 4 (MC4R), have been associated with early-onset obesity." (PMID 38664368, 2024). "Setmelanotide has been approved by the Food and Drug Administration and European Medicines Agency for treatment of rare monogenic obesity caused by pathogenic variants in genes upstream of MC4R." (PMID 38567654, 2024). "This review provides a background on the genetic aetiologies for obesity and focuses on setmelanotide, its mechanism of action, and its efficacy as a treatment for obesity secondary to a number of genetic variants in the POMC/MC4R pathway." (PMID 39526054, 2024). "The MC4R gene (rs17782313) not only influences obesity but is also associated with other risk factors for CVD, including hypertension (HTN)." (PMID 39104759, 2024). "GNAS mutations can variably impact height as impaired MC4R signalling can lead to obesity with tall stature, whereas impaired GHRH signalling results in GH deficiency and short stature." (PMID 39104441, 2024). "AgRP is a 112 amino acid peptide related to agouti, a mouse protein which, when mutated in a heterozygous state, causes yellow fur (due to MC1R antagonism) and obesity (due to MC4R antagonism)." (PMID 38019584, 2024).
Obesity (continued). "Mc4r−/− knockout mice develop severe hyperphagia and obesity, and dominant mutations in MC4R have been shown to be the most common cause of monogenic obesity in humans." (PMID 38019584, 2024). "For instance, a UK Biobank study showed that carriers of pathogenic MC4R variants with normal weight had a significantly lower polygenic risk score for BMI, compared to carriers with obesity." (PMID 38567654, 2024). "Here we have functionally analyzed 17 MC4R variants (1 homozygous, 1 compound heterozygous, and 15 heterozygous), identified in patients with severe obesity attending our Obesity Center CGG at Erasmus MC, Rotterdam, the Netherlands." (PMID 38567654, 2024). "The FTO and MC4R gene are two of the verified obesity-related variants, but evidence from ethnic minorities in China is limited." (PMID 38279121, 2024). "The prevalence of LoF MC4R variants ranges from 0.5% in adults with obesity to 5.8% in children with severe early-onset obesity." (PMID 38567654, 2024). "As mutations of the melanocortin 4 receptors (MC4R) are the leading monogenetic cause of obesity, MC4R haploinsufficient rats were fed a range of dietary fat (0–12 %) in a longitudinal design." (PMID 39741559, 2024). "POMC or MC4R deletion causes a severe metabolic phenotype characterized by severe obesity and hyperphagia in humans and mice, and MC4R haploinsufficiency in humans is the most common monogenic cause of obesity accounting for up to 5% of cases." (PMID 38992428, 2024). "Both modifiable environmental factors and MC4R gene polymorphisms were associated with the obesity risk in this population." (PMID 38279121, 2024). "During research, it was determined that a mutation in the melanocortin 4 receptor (MC4R) gene is linked to obesity and an increased risk of DM in cats." (PMID 39605770, 2024). "Based on the surveyed population, a 1:1 pair-matched case-control study was designed to determine the association between FTO (rs1121980 and rs17817449) and MC4R gene (rs17782313 and rs12970134) polymorphisms with obesity in Tibetan adults." (PMID 38279121, 2024). "It has been reported that MC4R was localized in the cilium of a subset of hypothalamic neurons, and obesity-associated MC4R mutations impaired its ciliary localization." (PMID 39621784, 2024). "Clinically, mutation carriers are characterized by severe obesity, severe hyperinsulinemia, increased lean body mass, and linear growth, whereas MC4R homozygous patients—although rarely identified—are more severely affected." (PMID 38397265, 2024). "In particular, MC4R became a drug target for weight control in severe forms of genetically caused obesity." (PMID 38906141, 2024). "Several polymorphisms of the MC4R gene have been reported to be associated with overeating and obesity." (PMID 39203789, 2024). "Disruption of the hypothalamic circuits controlling body weight and appetite caused by mutations in the genes encoding leptin, LEPR, POMC and MC4R can lead to severe obesity in humans." (PMID 39526054, 2024). "The MC4RF51L mutation produced a specific defect in MC4R/Gq/11α signaling and led to obesity, hyperphagia, and increased linear growth in mice." (PMID 38175730, 2024). "We set out to find new methods to specifically label the primary cilia of human iPSC-derived neurons, including cortical neurons and hypothalamic neurons reported to be enriched in obesity-associated GPCRs, such as the melanocortin 4 receptor (MC4R)." (PMID 38995007, 2024). "Three genes encode important components related to energy intake and energy expenditure balance such as Leptin (LEP), ghrelin (GHRL), melanocortin-4-receptor (MC4R), and the fat mass and obesity-associated gene (FTO)." (PMID 38863583, 2024). "A study on 300 patients showed that rs79783591 mutation increases obesity risk, but one functional MC4R copy allows short-term weight loss from dietary restriction, phentermine, and RYGB." (PMID 39125390, 2024).